ZEB1 (zinc finger E-box binding homeobox 1)
Diseases named in the same sentence as ZEB1 in open-access papers (continued):
Sharing a sentence is not in itself a finding about the gene and the disease.
lung adenocarcinoma (continued). "Some transcription factors including Slug, Zeb-1, Twist, Snail, and HIF1α, were predicted to be associated with EMT in lung adenocarcinoma based on both immunohistochemistry and in vitro experiments." (PMID 29568357, 2018). "As expected, we observed increased expression of mesenchymal markers Vimentin, Snail and Zeb1 and decreased expression of epithelial markers including E-cadherin and Claudin1 following treatment of lung adenocarcinoma cell lines with drugs." (PMID 28186986, 2017). "Here, the authors uncover a growth suppressive role for ZEB1 in EGFR mutant lung adenocarcinoma, thus elucidating the context dependent function of this protein." (PMID 27456471, 2016). "We recently showed that CIP4 promotes activation of an EGFR/ERK/Zeb1/MMP-2 axis in lung adenocarcinoma cells and tumors, and it will be interesting to further test this axis in CIP4 KD breast tumors." (PMID 25823823, 2015). "We also show that Zeb1 and Ets1 are expressed together at the invasive edge of K-Ras-initiated mouse lung adenocarcinomas, and there is a significant correlation between expression of Ets1 and Zeb1 in human lung adenocarcinoma." (PMID 25880398, 2015). "To check if Ets1 also follows Zeb1 expression in human lung adenocarcinomas, we examined microarrays of 59 human lung adenocarcinomas and compared expression of Ets1 and Zeb1 mRNAs." (PMID 25880398, 2015). "Consistent with such an amplification loop, we correlate expression of Ets1 and Zeb1 in mouse and human lung adenocarcinoma." (PMID 25880398, 2015). "Although the correlation between Ets1 and Zeb1 in lung adenocarcinoma seen above is consistent with an amplification loop between Ets1 and Zeb1, these results are also consistent simply with the previously documented induction of Zeb1 by Ets1." (PMID 25880398, 2015). "circRAPGEF5 enhances the progression of lung adenocarcinoma via the miR-1236-3p/ZEB1 pathway." (PMID 40429981, 2025). "Thus, ZEB1 activates a transcriptional program that controls lung adenocarcinoma cell adherence to Col1." (PMID 34874914, 2022). "Moreover, KIF5A mRNA levels were negatively correlated with miR-103a and positively correlated with ZEB1 in KP cells and in The Cancer Genome Atlas lung adenocarcinoma cohort." (PMID 34874914, 2022). "Moreover, the analysis of colony formation, cell apoptosis and γH2AX foci formation demonstrated that Biochanin A treatment enhanced the chemosentivity to cisplatin in lung adenocarcinoma cells, which in effect was mediated through downregulation of ZEB1." (PMID 36512117, 2022). "Importantly, Biochanin A chemosensitizes lung adenocarcinoma and inhibits cancer cell metastasis by suppressing ZEB1." (PMID 36512117, 2022). "Considering that ZEB1 functions as a key EMT transcriptional factor in tumor invasion and metastasis, we moved to validate whether Biochanin A affects cancer metastasis via the regulation of ZEB1 in lung adenocarcinoma." (PMID 36512117, 2022). "Furthermore, wound-healing and transwell assays demonstrated that Biochanin A inhibited cell migration and invasion in lung adenocarcinoma cells, which was mediated through the downregulation of ZEB1 expression." (PMID 36512117, 2022). "In addition, the expression of ATG5 was also positively correlated with the expression of Zeb1 in human lung adenocarcinoma." (PMID 33468994, 2021). "Furthermore, the expression of the master EMT-inducing transcriptional factor ZEB1 was significantly increased in DTX-resistant human lung adenocarcinoma cell line (SPC-A1/DTX)." (PMID 34445110, 2021). "Zotarolimus alone and zotarolimus combined with 5-FU reduced the metastatic ability of the A549 lung adenocarcinoma cells, which may be attributed to the decreased mRNA expression of ZEB1 (Figure A6)." (PMID 33925400, 2021).
lung adenocarcinoma (continued). "Interestingly, α1 integrinI (ITGA1) mRNA and adenylyl cyclase 9 (ADCY9) mRNA competed for binding to miR-181b, and ZEB1 upregulated ITGA1 to activate a miR-181b-regulated ceRNA network that increased metastasis of lung adenocarcinomas." (PMID 33741027, 2021). "In addition to A549 cells, ZEB1 was also elevated in PHRF1-transfected lung adenocarcinoma CL1-0 and CL1-5 cells." (PMID 32730336, 2020). "In the present work, we demonstrate for the first time that AGR2 and ZEB1 expression shows an inverse correlation in lung adenocarcinomas, since AGR2 is usually overexpressed in tumor tissue as compared to the normal tissues, while ZEB1 shows the opposite trend." (PMID 32570918, 2020). "Moreover, we examined the expression of AGR2 and ZEB1 in normal lung tissues and lung adenocarcinoma tissues using the public database Oncomine." (PMID 32570918, 2020). "Moreover, hsa-mir-33b can inhibit lung adenocarcinoma cell growth, invasion, and epithelial-mesenchymal transition by suppressing Wnt/β-catenin/ZEB1 signaling." (PMID 31019967, 2019). "In vivo, ERBB3 is repressed in lung adenocarcinoma tissue with elevated ZEB1 expression." (PMID 27456471, 2016). "Next, we expressed ZEB1 in lung adenocarcinoma cells, including H441, 393P, HCC827 and H3255 cells." (PMID 27456471, 2016). "We examine expression of Ets1 and Zeb1 in K-Ras initiated mouse lung adenocarcinomas." (PMID 25880398, 2015). "However, the expression of TWIST and SNAIL were not affected, highlighting that Biochanin A might perform a specific inhibitory effect on the malignant progression of lung adenocarcinoma through ZEB1." (PMID 36512117, 2022). "Overall, our data reveal an important physiological role for S100-A15 in comprehending the proliferative, metastatic, and invasive properties of lung adenocarcinoma which may be orchestrated by CTNNB1 with the involvement of ZEB1, CDC42, HSP90AA1, PCNA and BST2." (PMID 28498804, 2017). "In addition, silencing ZEB1 expression could significantly restore the chemosensitivity of docetaxel-resistant human lung adenocarcinoma cells as well as inhibit their migratory ability through reversing the mesenchymal phenotype." (PMID 29245917, 2017). "Qu and colleagues discovered that miR-33b expression was dramatically decreased in lung adenocarcinoma cell lines and tissues, and this reduced expression was associated with tumor lymph node metastasis mediated in part by the binding of miR-33b to the ZEB1 3′UTR region inhibiting ZEB1 expression." (PMID 26784241, 2016). "In lung adenocarcinoma cells, NEK4 acts as a promoter of EMT by regulating the activity of suppressor of mothers against decapentaplegic 3 (SMAD3) and zinc finger E-box binding homeobox 1 (ZEB1) during transcriptional growth factor beta (TGF-β)-induced EMT." (PMID 41154634, 2025). "Neutrophils also secrete transforming growth factor (TGF)-beta, upregulating transcription factors such as Snail1/2, Zeb1/2, and Twist1, which drive EMT and promote lung adenocarcinoma development." (PMID 40870429, 2025). "PIK3C2B expression showed significant positive correlations with key EMT regulators: SNAI1 (r = 0.11, p = 0.00098), VIM (r = 0.21, p = 1e-10), ZEB1 (r = 0.37, p = 6.7e-33), and TWIST2 (r = 0.11, p = 0.00034) in TCGA lung adenocarcinoma samples." (PMID 41362647, 2025). "Specifically, EMT was induced in human NSCLC A549 cells by NiCl2, leading to the upregulation of ZEB1, while other EMT drivers remained unchanged, underscoring ZEB1’s primary role in the EMT pathway in lung adenocarcinoma cells." (PMID 39409891, 2024). "In cytoplasm, MALAT1 weakens the binding of miR-200b to E2F transcription factor 3(E2F3) and ZEB1 mRNAs, thus leading to increase of E2F3 and ZEB1 protein expression and chemoresistance of lung adenocarcinoma cells." (PMID 34976181, 2022).
lung adenocarcinoma (continued). "Previous studies also reported that the Wnt/β-catenin pathway contributes to the induction of EMT by transactivating several EMT-related transcriptional factors, such as Snail, Slug, Twist, ZEB1, and ZEB2 in lung adenocarcinoma." (PMID 34497759, 2021). "The transcriptional product of TSPAN4 is a circular RNA that is upregulated in lung adenocarcinoma; circ-TSPAN4 can promote metastasis by increasing the expression of ZEB1." (PMID 34917619, 2021). "Previous studies have shown that miR‐33b prevented lung adenocarcinoma cell viability, invasion, and EMT by inhibiting the Wnt/β‐catenin/ZEB1 pathway." (PMID 31515968, 2020). "Our previous study showed that miR-33b was downregulated in lung adenocarcinoma cells and that reduced miR-33b expression stimulated ZEB1 expression, which led to WNT/β-catenin signaling pathway activation and thus promoted lung adenocarcinoma progression." (PMID 29383119, 2017). "In general, downregulation of ZEB1, RECK, TGFBR2 and BMPR2, as well as upregulation of CDK4, CCNE2, EZH2 and DNMT1 has been shown in lung adenocarcinoma and/or squamous cell carcinoma." (PMID 27588394, 2016). "To validate these observations, we quantified the expression of ZEB1, CDH1 and VIM for 41 paired samples of lung adenocarcinoma and adjacent normal lung tissues." (PMID 27456471, 2016). "ZEB1 knockdown reverses the EMT phenotype, inhibits migratory ability and enhances the chemosensitivity of docetaxel-resistant human lung adenocarcinoma cells." (PMID 25890268, 2015). "Similarly, expression of mesenchymal markers including Vimentin and Zeb1 were significantly increased following EerI treatment and returned to basal level after PP2 treatment further providing evidence that PP2 blocks ER stress and its associated EMT in lung adenocarcinoma cells." (PMID 25970786, 2015). "Expression of TWIST1, mesenchymal (CDH2, VIM, SNAI1, ZEB1) and epithelial (CDH1, JUP) markers in lung adenocarcinoma cell lines." (PMID 22272264, 2012). "Additionally, analysis of The Cancer Genome Atlas (TCGA) data for lung adenocarcinoma (LUAD) revealed a positive correlation between ITIH2 and ZEB1 mRNA levels." (PMID 40178908, 2025). "However, despite obvious induction of EMT markers ZEB1 and SLUG in human lung adenocarcinoma cell lines stimulated with TGFβ, transcription of HS2/HS3 was reduced." (PMID 36635266, 2023). "To investigate the mechanistic basis for PI4K2A’s positive correlation with EMT, we used a panel of human lung adenocarcinoma (LUAD) and lung squamous carcinoma (LUSC) cell lines that have been classified as epithelial or mesenchymal and in which high ZEB1 levels maintain a partial EMT." (PMID 36757799, 2023). "In the literature, where the differences and additional functions of proteins involved in EMT were compiled, it was reported that Slug expression increased in hypoxic lung adenocarcinoma tissue, but ZEB1 expression did not change." (PMID 35201505, 2022). "We then explored the regulatory mechanism of miR-183 and found that it may be involved in the regulation of zinc finger E-box-binding homeobox 1 (ZEB1) expression and mediate EMT in lung adenocarcinoma cells." (PMID 33825780, 2021). "Consistently, immunohistochemical staining results showed that lung adenocarcinoma cells expressed high levels of E-cadherin but low to non-detectable levels of Vimentin and ZEB1." (PMID 27456471, 2016). "Furthermore, LncRNA NCBP2-AS2 was upregulated in lung squamous cell carcinoma samples compared with lung adenocarcinoma samples and adjacent tissues and promoted cell proliferation and metastasis, as well as the invasive and inhibited apoptosis of SCC cells via the TAp63/ZEB1-regulating pathway." (PMID 36010268, 2022). "Similar outputs were also obtained by data mining from The Cancer Genome Atlas (TCGA) cohorts for lung adenocarcinoma, demonstrating a significant negative correlation between AGR2 and ZEB1 (p < 0.001)." (PMID 32570918, 2020).
cervical carcinoma (72 papers, 2014 to 2025). A carcinoma arising from either the exocervical squamous epithelium or the endocervical glandular epithelium. "In connection with CCL8 it has already been shown that ZEB1, induced by hypoxia, promotes the progression of cervical cancer through CCL8-dependent tumor-associated macrophage recruitment." (PMID 34833360, 2021). "Clinically, ZEB1 expression was found in over 95% cervical cancer and the expression level was significantly associated with International Federation of Gynecology and Obstetrics (FIGO) stages and regional lymph node metastasis." (PMID 25197668, 2014). "The expression levels of ZEB1 and CrkL exhibited an inverse correlation with miR-429 levels in cervical cancer cell lines." (PMID 40362257, 2025). "In cervical cancer cell lines, ZEB1 and CrkL expression levels were found to be inversely correlated to the levels of miR-429." (PMID 40362257, 2025). "In cervical cancer, miR-429 played a role in reducing colony formation via the ZEB1 and CrkL signaling pathways." (PMID 40362257, 2025). "For example, ZEB1 has been shown to promote the EMT progression via its ability to induce transcriptional regulation in cervical cancer." (PMID 39473907, 2024). "In summary, we demonstrated that ESM1 was correlated with the malignant progression of cervical cancer through ZEB1/EMT axis, and ESM1 was a key regulatory protein during the cervical cancer progression." (PMID 38954708, 2024). "In line with this, our knock down of SDHC or SDHD in cervical cancer cells increased the expression of vimentin, ZEB1 and TWIST, but reduced e‐cadherin." (PMID 37899663, 2024). "HAGLR was also found to upregulate zinc finger E-box binding homeobox 1 (ZEB1) through binding with miR-130a-3p to promote resistance to cisplatin (chemotherapy medication used to treat several types of cancers) in cervical cancer." (PMID 37624034, 2023). "Recent studies have also found that UBE2C/ZEB1/2 signal axis plays an important role in the metastasis and AR in cervical cancer." (PMID 37081871, 2023). "On the other hand, CCL8-mediated TAM infiltration contributes to hypoxic ZEB1-related cancer progression and poor prognosis in cervical cancer." (PMID 36670988, 2023). "Regarding its function in cervical cancer, ZEB1, which has been identified as a common gene controlled by the miR-200b/429 cluster, requires more investigation." (PMID 36879084, 2023). "Further supporting ZEB1’s role, TRIM29 was downregulated in MTD-treated cells and its protein is associated with increased ZEB1 expression and EMT in cervical cancer cells." (PMID 37239838, 2023). "In this context, it has been reported that hypoxia increases ZEB1 expression in cervical cancer cells, which directly promotes CCL8 production and induces macrophage infiltration, mainly into hypoxic areas, via the CCR2–NF-κB pathway." (PMID 36670988, 2023). "Their reports point out that miR-126 can affect the biological functions of osteosarcoma and cervical cancer cells by regulating the expression of ZEB1, thus participating in the development of tumors." (PMID 35582235, 2022). "In cervical cancer, CCL8 causes the recruitment of TAM through interactions with ZEB1 in hypoxic cancer cells." (PMID 36072582, 2022). "Among these target genes, ZEB1 has been reported to regulate the EMT of cancer cells in cervical carcinoma and esophageal squamous cell carcinoma." (PMID 35186455, 2022). "Previous conclusions show that lncRNA-SNHG16 can regulate miR-216a-5p/ZEB1 and promote tumor development in cervical cancer tissues, which partly supports our results." (PMID 36248798, 2022). "LncRNA TMPO-AS1 promoted proliferation, migration, and invasion of cervical cancer cell by regulating the miR-143-3p/ZEB1 axis." (PMID 36561319, 2022).
cervical carcinoma (continued). "This is consistent with a previous investigation showing that M2-like TAMs in the stroma always surround Zeb1-positive cells in ovarian and cervical cancers, supporting the potent roles of Zeb1 in the recruitment and polarization of M2-like TAMs." (PMID 35246504, 2022). "Next, we examined the expression of EMT-related proteins, including E-cadherin, N-cadherin, vimentin, ZEB1, twist, and snail, to explore the underlying mechanism by which FAM83A promotes the invasion of cervical cancer cells." (PMID 34659522, 2021). "Our data clearly showed that APE1 stimulates ZEB1 and E-cadherin promoter binding by directly binding to ZEB1, thereby inhibiting E-cadherin expression in cervical cancer cells." (PMID 34210327, 2021). "Circ-ABCB10 acts as a sponge for miR-128, which in turn results in an increase in its direct target ZEB1, leading to augmented cell proliferation, migration, invasion, and inhibition of apoptosis in cervical cancer." (PMID 34884646, 2021). "In SiHa and CaSki cervical cancer cell lines, 10 μM TQ has shown an ability to suppress the cancer metastasis, migration, and invasion by reducing Twist1 and Zeb1 expression and inducing E-cadherin expression in a dose- and time-dependent manner." (PMID 33923474, 2021). "Our study suggests that circ-ABCB10 depletion inhibits proliferation, invasion and EMT and promotes apoptosis of cervical cancer cells through miR-128-3p/ZEB1 axis and represses CC tumor growth." (PMID 34493213, 2021). "A de–regulation of Wnt signaling was also reported for liver and cervical cancer, associated with a reduction of EMT markers such as SNAI1, SNAI2, ZEB1 or VIM in cervical cancer–derived cell lines." (PMID 34062997, 2021). "Consistent with this, ZEB1 silencing inhibits cervical cancer cell EMT and metastasis, suggesting that ZEB1 is a potential therapeutic target for EMT-induced cervical cancer metastasis treatment." (PMID 34210327, 2021). "It was presumed that the interaction of miR-203 with ZEB1 should contribute to stemness acquisition of cervical cancer cells." (PMID 34539782, 2021). "Specifically, it is shown that SNAI1, along with ZEB1, regulated the epithelial–mesenchymal transition and was then involved in the metastasis of cervical cancer." (PMID 34149809, 2021). "Our data showed that APX3330 inhibits ZEB1 and E-cadherin promoter binding, thereby restoring the E-cadherin expression inhibited by ZEB1 in cervical cancer cells." (PMID 34210327, 2021). "PCAT6 also enhances chemoresistance to cisplatin in cervical cancer by sponging miR-543 and activating ZEB1 expression." (PMID 34277403, 2021). "Hypoxia can enhance ZEB1 expression and promote cervical carcinoma progression through increased CCL8 secretion and tumor-associated macrophage recruitment." (PMID 32185181, 2020). "To further investigate ZEB1 function on macrophage migration, we established ZEB1-overexpressing normoxic cervical cancer cells and ZEB1-silenced hypoxic cervical cancer cells." (PMID 31263103, 2019). "ZEB1 switches with cervical cancer as a target of several miRNAs, such as miR-211, miR-429 and miR-484." (PMID 31007650, 2019). "Collectively, the results led us to conclude that levels of ZEB1 were upregulated in the hypoxic area of human cervical cancer specimens, which in turn coincided with higher accumulation of CD163+ TAMs." (PMID 31263103, 2019). "We analysed the effect of hypoxia on ZEB1 expression in cervical cancer cells (SiHa and C33a) in vitro with immunofluorescence staining and western blotting." (PMID 31263103, 2019). "Our study revealed a possible mechanism of TAM infiltration into the hypoxic tumour zone via ZEB1-driven cervical cancer cells." (PMID 31263103, 2019). "We also found that ZEB1 was highly expressed in hypoxic cervical cancer cell islets, which are known to display a stronger pro-tumour phenotype." (PMID 31263103, 2019). "miR-126 and ZEB1 were found to be involved in regulating cell proliferation, migration and invasion of cervical cancer." (PMID 31007650, 2019).